LEP (leptin)
Diseases named in the same sentence as LEP in open-access papers (continued):
Sharing a sentence is not in itself a finding about the gene and the disease.
Obesity (continued). "Moreover, increased leptin levels also promote glycolysis in CD8+ T cells via PI3K/Akt/mTOR pathway, which partly accounts for obesity-induced chronic inflammation." (PMID 37266440, 2023). "Leptin activates the nicotinamide adenine dinucleotide phosphate (NADPH) oxidase, stimulates the production of reactive oxygen species (such as hydrogen peroxide, H2O2), also increases oxidative stress in obesity." (PMID 37921934, 2023). "In addition to increased RV afterload due to obesity-related LVDD, circulating cytokines, growth hormones, adipokines (leptin, Ang II, insulin, and aldosterone), BP, and nocturnal hypoxemia contribute to obesity-related RV remodeling." (PMID 37176781, 2023). "Second, in addition to BMI, defining obesity, and circulating maternal leptin as proxy for adiposity, we included maternal glucose, C-peptide and ISHOMA as metabolic exposures since a proportion of individuals with obesity may be metabolically ‘healthy’." (PMID 37029207, 2023). "Hyperleptinemia is a possible mechanism for reducing DNL enzymes in obesity-related WAT58, but whether leptin plays the same role in BAs after UDN or thermoneutrality is unclear." (PMID 37179330, 2023). "The main objective of this study was to verify the effects of weight loss induced by RYGB on the circulating levels of systemic inflammatory markers adiponectin, resistin, leptin, TNF-alpha, IL1-beta interleukins, IL-6, IL-8, IL-17, IL-23 and IGF-1 in women with severe obesity and MS." (PMID 36788619, 2023). "The PBMC cultures were stimulated with Fel d1 antigen (10 μg/mL) in the presence or absence of obesity-related leptin dose (50 ηg/mL)." (PMID 37954580, 2023). "Results of this trial showed significant reductions in obesity indices and total and visceral fat without any significant change in serum leptin and adiponectin levels." (PMID 37476001, 2023). "Lastly, a major early but disappointing finding was that exogenous leptin administration failed to reverse obesity." (PMID 36769012, 2023). "Leptin (LEP) is an adipokine that due to its influence on the regulation of appetite and energy homeostasis attracts interest among researchers dealing with obesity and MetS." (PMID 37109160, 2023). "Furthermore, a notable decline in weight increase and a drop in plasma concentrations of leptin, triglycerides, insulin, and glucose were observed in cases of NAFLD induced by fipronil or obesity, in comparison to the control group." (PMID 37958712, 2023). "Unlike leptin, blood adiponectin levels are thought to be inversely related to obesity and therefore should decrease in the course of HFD consumption." (PMID 36768493, 2023). "Our findings indicate that 12 weeks of HIFT supplemented with spinach-derived thylakoid reduced levels of leptin, resistin, vaspin, visfatin, apelin, RBP4, chemrin, semaphorin3c and insulin resistance while increasing adiponectin and omentin levels in men with obesity." (PMID 37576981, 2023). "Moreover, obesity also intricately influences the RAAS and leptin signaling, impacting blood pressure regulation." (PMID 37987283, 2023). "Our data revealed heterogeneous plasma levels of adiponectin and leptin in patients with obesity without significant differences between patients with versus without OSAS." (PMID 36921085, 2023). "Metreleptin is contraindicated in patients with general, nongenetic obesity that does not result from internal leptin defects because externally derived obesity is unrelated to a leptin problem, rendering leptin analogs resistant for these patients." (PMID 37937009, 2023). "We confirmed that leptin levels corresponding to serum concentrations found in obesity (50–100 ng/ml) disrupt apical localization of ZO-1 in non-neoplastic acini." (PMID 37160903, 2023).
Obesity (continued). "Further, these alterations in gut microbiota have been shown to promote important changes in satiation signals including gut hormones (leptin, ghrelin, GLP-1, peptide YY and CCK) and orexigenic and anorexigenic neuropeptides (AgRP, NPY, POMC, CART) that influence hyperphagia and therefore obesity." (PMID 37571301, 2023). "With a prevalence of obesity that exhibits hyperleptinemia, most of the investigation on leptin has been focused on how it works and how it does not, which is expected to be a clue for treating obesity." (PMID 37547309, 2023). "Leptin's multiple mechanisms of resistance make leptin less of an ideal target the reason why there are no drugs on the market for the treatment of diet-based or externally derived obesity." (PMID 37937009, 2023). "Actually, leptin and HSL are excellent biomarkers for body fat content and related to disorders of glucose and lipid metabolism, such as insulin resistance, type-2 diabetes, and obesity." (PMID 36836789, 2023). "Hence, the objective of this study was to evaluate the effect of leptin on ROS generation and on the antioxidant system, in a primary culture of SMC derived from the aorta of a model of sucrose-diet induced obesity." (PMID 36978976, 2023). "Leptin positively regulates these SNS neurons through MBH-localized AgRP/NPY-, POMC/CART-, and SH2B-expressing neurons since deletion of LepR in those neurons results in obesity with the inefficiency of thermogenesis and lipolysis." (PMID 37547309, 2023). "This was supported by a study comparing leptin levels during fasting in people with obesity to those without." (PMID 37049602, 2023). "This study does not reveal if increased leptin is a marker for obesity or has a more active role within the pathophysiological mechanism of chronic widespread pain." (PMID 37559026, 2023). "The expected anorexic responses have not been observed in obesity with elevated leptin levels, suggesting a leptin resistance." (PMID 36674022, 2023). "Other biological mechanisms, such as neuroendocrine changes in the leptin-melanocortin pathway and overlapping genetic variation (e.g., OLFM4 and NEGR1), could also explain the correlation between obesity and depression." (PMID 37621933, 2023). "Factors apt for further investigation include the extent to which PCOS phenotypes, BMI, obesity, insulin resistance, hyperandrogenemia, SHBG, hs-CRP, CTRP6, adiponectin, plasma leptin, homocysteine, AMH and thrombophilia contribute to further risk of miscarriage." (PMID 38027110, 2023). "Other adipokines that are positively correlated with obesity (leptin, resistin, vaspin, chemerin, nesfatin) do not exhibit an equivocal role in carcinogenesis." (PMID 37048738, 2023). "Therefore, this study aimed to compare the levels of LEP and ADP across different obesity phenotypes and healthy controls, and further investigated the association between these adipokines with different obesity phenotypes." (PMID 37853077, 2023). "Treatment with leptin downregulates these miRNAs, and hipotalamic silencing of miR-200a increases expression of LEPR and ISR-2 (insulin receptor substrate 2), suggesting that this miRNA can be a target for obesity treatment." (PMID 37375898, 2023). "In conclusion, leptin is not the ideal drug target for treating obesity unless indicated specifically for congenital/acquired generalized lipodystrophy." (PMID 37937009, 2023). "In mice lacking LepRb or those with diet-induced obesity, leptin, when taken up by tanycytes, tends to accumulate in the median eminence, failing to reach the ARH." (PMID 38027481, 2023). "Leptin has been reported to increase airway inflammation in an allergic asthma mouse model without obesity." (PMID 37488474, 2023). "In contrast, those without obesity began with leptin levels around 11 ng/mL, and after 24 h of fasting, the levels decreased to around 4 ng/mL." (PMID 37049602, 2023).
Obesity (continued). "The absence of leptin leads to increased lipid synthesis and decreased lipid oxidation, setting the stage for obesity, dyslipidemia, and NAFLD development in Lepob/ob mice." (PMID 36599953, 2023). "The authors determined the level of Expression of Leptin (LEP) in Polycystic Ovary Syndrome (PCOS) patients with or without obesity and in GCs treated with insulin." (PMID 37562217, 2023). "Metreleptin, therefore, bypasses the possibility of leptin resistance due to its indication for patients only with genetic defects in leptin who lack central leptin resistance, a type of resistance seen in nongenetic obesity." (PMID 37937009, 2023). "In addition, lactate accumulation in obesity accelerates renal urate reabsorption via urate transporter 1 (URAT1), and the obesity gene product leptin can affect the renal clearance of uric acid." (PMID 37747198, 2023). "This study focused on the interpretation of ghrelin and leptin concentrations 6 months after COVID-19 infection in patients without obesity, with a mild course of the disease." (PMID 37240656, 2023). "In obesity, oxidative stress, along with the release of pro-inflammatory cytokines, such as leptin, IL-6, and TNF-α from adipose tissue, can lead to NAFLD, non-alcoholic steatohepatitis, fibrosis, and liver cirrhosis progression." (PMID 37246210, 2023). "In many cases of obesity, the elevated NPY-ergic tone may be due to central resistance to peripheral signals of energy excess such as leptin, which increases with long-term exposure to positive energy balance." (PMID 37452264, 2023). "Furthermore, obesity, hypertension, metabolic syndrome, and endothelial dysfunction are more frequent in T2DM patients with increased leptin levels." (PMID 36901837, 2023). "Both physiological and biochemical data initially indicated that the explanation for the obesity in these mice should be the absence of a thermogenic effect of leptin that in its turn should have occurred through activation of brown adipose tissue." (PMID 37661736, 2023). "Despite these alterations, no significant variations in serum levels of leptin, triglycerides, or cholesterol were observed between the diet-induced obesity (DIO)-challenged IRcKO mice and control animals." (PMID 38071352, 2023). "Diet-induced obesity increases the activation of inflammation in the mediobasal hypothalamus, resulting in the production of proinflammatory cytokines (TNF-α, IL-1β, and IL-6) and impairment in insulin and leptin signaling." (PMID 36677011, 2023). "Leptin and adiponectin have been considered as prognostic factors for the progression of cardiometabolic disorders in patients with overweight/obesity, but information is lacking or controversial in CKD patients." (PMID 36967775, 2023). "RT-PCR and WB assays showed that LEP levels were not altered in the ovaries of PCOS patients without obesity and in females from the control group." (PMID 37562217, 2023). "LEP expression was first assessed in ovary cortex specimens collected from women with PCOS with or without obesity as well as from healthy controls." (PMID 37562217, 2023). "Supplementation with CTE did not prevent the obesity-induced increase in glycaemia but it significantly reduced the plasma concentrations of leptin (p < 0.01), adiponectin (p < 0.05) and insulin (p < 0.05), as well as the HOMA-IR (p < 0.05)." (PMID 37239868, 2023). "Moreover, miR-26b is downregulated by leptin and this miRNA was found to be reduced in visceral adipose tissue (VAT) in insulin-resistant adipocytes, obese rodent models, and human obesity." (PMID 36674935, 2023). "The effect of obesity without leptin signaling was modeled by comparing female lean Zucker rats to pair fed obese Zucker rats, which possess mutant fa alleles of the leptin receptor gene." (PMID 37457883, 2023).
Obesity (continued). "In mice, diet-induced obesity in the pubertal period, but not in adulthood, resulted in elevated leptin expression in mammary adipose tissue along with stunted mammary ducts and reduced MEC proliferation." (PMID 37173058, 2023). "For example, it has been found in animals that maternal obesity and maternal consumption of HFD in lactation increases hypothalamic expression (mRNA and protein) of NPY and AgRP, whereas reduces POMC expression and decreases sensitivity to leptin." (PMID 37252665, 2023). "A negative relationship between obesity and progesterone levels was demonstrated during the first trimester which can in part be explained by the effect of leptin on reducing progesterone secretion." (PMID 36520252, 2023). "In contrast, the highest leptin levels were in children with overweight/obesity without MetS (18.17; IQR 11.74–29.17 ng/mL) and the lowest were in those with normal body weight (2.31; IQR 1.47–4.90 ng/mL)." (PMID 36920931, 2023). "Mice lacking SOCS3 in the brain or POMC neurons display improved leptin sensitivity and resistance to diet-induced obesity." (PMID 38027481, 2023). "In addition, ER stress inhibitors improve leptin sensitivity and attenuate obesity by suppressing hypothalamic IKKβ/NF-κB and increasing STAT-JAK as a leptin sensitizers in mice." (PMID 38084147, 2023). "Adipose tissue hormones such as leptin are independent of the lactotrophic and corticotropic axes but similar to corticosteroids and can influence obesity by regulating appetite." (PMID 37241010, 2023). "Leptin, the product of the OB(Obesity) gene, is a 16 kDa non-glycosylated peptide hormone which is synthesized almost exclusively by adipocytes that regulate appetite and energy expenditure at the hypothalamic level." (PMID 37378223, 2023). "Serum leptin, resistin, PAI-1, and CRP levels differed significantly between children with normal body weight and those with overweight/obesity, and between those with and without MetS (all p<0.05), being higher in children with overweight/obesity and MetS." (PMID 36920931, 2023). "Overall, in vivo investigations demonstrated the positive correlation between obesity and ovarian cancer, although some of those did not investigate circulating leptin levels." (PMID 37509120, 2023). "Leptin alteration has also been found in metabolic diseases or obesity, but not everyone with leptin abnormalities develops vitiligo." (PMID 37207234, 2023). "Further evidence for the presence of the obesity paradox in HF patients is the lack of correlation between leptin and TNFr1 harboring a death domain in obese patients with HF." (PMID 36428528, 2022). "In the context of therapies that seek to chronically increase leptin sensitivity for the treatment of obesity, these potentially negative aspects need to be considered and carefully evaluated in pre-clinical and clinical studies." (PMID 35742928, 2022). "We hypothesize that Metreleptin might be a treatment option in children with obesity, NAFLD and with low z-scores of circulating leptin levels with the aim to improve fatty infiltration and hepatic inflammation." (PMID 35677722, 2022). "Although leptin brain uptake has been noted in regions not shielded by the BBB, the necessity of leptin BBB penetration has been confirmed in preclinical obesity models." (PMID 36131285, 2022). "Understanding the leptin induced suppression of GLP‐1 inputs to the hypothalamus during weight gain and/or in the obese state may provide an additional pathology of obesity and diabetes." (PMID 34519026, 2022). "More interestingly, alteration in Rcan2 levels was previously found to be correlated with the development of tumor, whereas Rcan2 is also known to regulate the obesity progression via a mechanism-independent of leptin signaling." (PMID 36267816, 2022). "A higher adiponectin/leptin ratio was the only statistically significant difference between asthma patients with and without obesity." (PMID 35807067, 2022).
Obesity (continued). "Although there was a significant mean difference among the EDII median for leptin (P=0.03), after further controlling with economic status and education, starting obesity age, there was no significant mean difference for leptin resistance (P=0.21)." (PMID 36151575, 2022). "It was demonstrated that the Ala alelle polymorphism in the obese male patients, but not female, was positively correlated with obesity-related parameters, such as BMI and plasma leptin levels." (PMID 36551995, 2022). "Negative correlations between leptin, 25(OH)D, and body composition appeared clearly in boys and girls when using %BF at 30 and 40 to classify their degrees of obesity." (PMID 35721764, 2022). "Taken together, our results revealed that all high dietary fatty acid diets induced obesity accompanied by lipid disorders, intestinal barrier dysfunction, and changes in secreted cytokines from gut-brain axis including BDNF, 5-HT, leptin, insulin, and ghrelin." (PMID 35739547, 2022). "Leptin failed to improve insulin sensitivity in T2DM patients with obesity due to hyperleptinemia and leptin resistance." (PMID 34996484, 2022). "However, impaired leptin BBB transport has been demonstrated in obese subjects and contributes to functional and behavioral changes related to obesity." (PMID 36131285, 2022). "Due to the absence of circulating leptin, db/db mice develop significant obesity along with β cell dysfunction due to increased ER stress." (PMID 35298439, 2022). "Patients with obesity often display hyperleptinemia and leptin resistance, whereas this condition is certainly absent in ob/ob mice." (PMID 35252310, 2022). "Although leptin is elevated in humans with obesity, these elevated levels do not influence reducing obesity." (PMID 36213285, 2022). "Deferasirox was also effective in established obesity and in ob/ob mice, indicating that intact leptin signalling is not needed for efficacy." (PMID 35031684, 2022). "In early-pubertal girls with obesity (not prepubertal girls), there was a positive correlation (p < 0.01) between leptin levels with LH, androstenedione and testosterone, and HOMA-IR with LH and testosterone levels." (PMID 35412268, 2022). "In T2DM and obesity, the adipocytes of expanded EAT release large amounts of FAs that trigger macrophage infiltration and secretion of pro-inflammatory adipocytokines including leptin, TNF-α, IL-6, IL-1b and resistin." (PMID 35204677, 2022). "While the majority of patients with obesity did not benefit from this treatment, patients with reduced basal leptin levels showed an improved reduction in fat mass or body weight under treatment with Metreleptin." (PMID 35677722, 2022). "To explore the medicative effect of LF on obesity-related fertility problems, we examined the ob/ob mice lacking leptin genes." (PMID 35267914, 2022). "The effect of leptin variants namely LEP rs2167270 and LEP rs4731426 that increased CRC risk independent of obesity in females is reduced by estrogen treatment." (PMID 36429114, 2022). "On the other hand, in ageing mice fed HFD, the lack of TRPV1 promotes obesity due to altered energy balance and leptin resistance." (PMID 35455971, 2022). "Notably, patients with obesity and patients with obesity and diabetes showed significantly higher BMI, WHR, fasting insulin, hsCRP and leptin and significantly lower HDL-cholesterol and adiponectin levels than Control subjects." (PMID 35585213, 2022). "Increasing evidence has shown a strong interconnection between ER stress and the pathology of obesity and T2DM that may lead to leptin and insulin resistance." (PMID 35103058, 2022). "Mice with two copies of the non-functional mutant leptin gene (ob/ob) or mutant leptin receptor gene (db/db) develop hyperphagia and obesity, despite consuming a normal chow diet." (PMID 36077188, 2022).